CDK1 (cyclin dependent kinase 1)
Diseases named in the same sentence as CDK1 in open-access papers (continued):
Sharing a sentence is not in itself a finding about the gene and the disease.
tumor (continued). "Together, our results uncover a novel cell cycle independent function of CDK1 to promote tumor progression through stabilizing TWIST1 in TNBC." (PMID 36782089, 2023). "Endothelial cells and fibroblasts mainly acted as signal senders, while macrophages, CDK1/stromal cluster cells, tumor cells, and CDK1/tumor cluster cells mainly acted as receivers." (PMID 36950551, 2023). "There was a moderate positive correlation between tumor purity and CDK1/PBK/CHEK1 with a Rho of 0.474, 0.459, and 0.513." (PMID 38003585, 2023). "Because of the significant role it plays in one of the phases of cell cycle control, which is a crucial one for the growth of tumor cells, specifically targeting CDK1 became a strategic focus for optimized treatment." (PMID 38099190, 2023). "Most importantly, the inhibition of CDK1 via knockdown partially counteracted the tumor growth enhancement induced by HADHA elevation." (PMID 37986001, 2023). "Then, a systematic analysis was performed to explore the relationships of CDK1 with clinical characteristics and tumor immune microenvironment factors in LUAD." (PMID 36950551, 2023). "4E-BP1 is a tumor suppressor regulating cap-dependent translation that is in turn controlled by mechanistic target of rapamycin (mTOR) or cyclin-dependent kinase 1 (CDK1) phosphorylation." (PMID 37145994, 2023). "The expression levels of ACADL, ACADS, ACADSB, ALDH6A1, ETFDH, and GCDH were found to be lower in tumor samples compared to normal samples, whereas the expression levels of CCNB1 and CDK1 were observed to be higher in tumor than in normal samples." (PMID 37994323, 2023). "Here, we next performed a comprehensive analysis to investigate the relationship between CDK1 expression and tumor immune microenvironment factors, including lymphocytes, checkpoints, MHC molecules, chemokines and receptors." (PMID 36950551, 2023). "The relationship between CDK1 expression and the tumor microenvironment is complicated, and the tumor microenvironment reshaped by CDK1 is the result of interactions between multiple immune-associated molecules." (PMID 36950551, 2023). "Studies showed that anti-CDK1 therapy enhanced the anti-tumor response of sorafenib in HCC patient derived xenograft (PDX) model, and provided a reasonable combination therapy to improve the clinical efficacy of sorafenib." (PMID 37393234, 2023). "The exception to this is RO-3306, a selective, ATP-competitive, and cell-permeable CDK1 inhibitor that demonstrates potent anti-tumor activity in multiple pre-clinical models." (PMID 37569750, 2023). "It has been reported that cyclin B1/CDK1-mediated mitochondrial bioenergetics plays a role in tumor cell survival and the reduction in anticancer efficacy." (PMID 35681641, 2022). "The correlations between CDK1 expression and the ESTIMATEScore, the ImmuneScore, and the StromalScore were estimated using SangerBox in diverse tumor types from the TCGA database." (PMID 35681641, 2022). "SET regulates the G2/M transition by modulating CDK1, and it results in tumor progression and poor clinical outcomes in GC." (PMID 35406376, 2022). "Collectively these results show that dimeric PKM2 uses its pY-binding ability to increase Cdk1-cyclin B activation to facilitate tumor cell entry into mitosis." (PMID 35392228, 2022). "The key drugs retrieved were members of anthracyclines, mitotic inhibitors, anti-tumor antibiotics, and CDK1 inhibitors." (PMID 35831333, 2022). "Based on the importance of CDK1 in antitumor immunotherapy and reversal of chemotherapy resistance, CDK1 can be an important factor in measuring the efficacy of tumor immunotherapy and chemotherapy." (PMID 36090896, 2022).
tumor (continued). "The analysis showed that CDK1 expression was significantly upregulated in various tumor tissues compared to the expression in the adjacent normal tissues." (PMID 36090896, 2022). "In this study, we determined the role of CDK1 in tumorigenesis from the perspective of clinical tumor samples." (PMID 36090896, 2022). "The protein expression level of CDK1 in tumor tissues was higher than that in normal tissues, which was consistent with the sequencing results." (PMID 35517403, 2022). "Exploring the specific signaling pathway of CDK1 and developing targeted drugs is a potential anti-tumor drug research direction." (PMID 36078096, 2022). "Most notably, the tumor suppressor miR-129 has been shown to suppress expression of CDK1 and iASPP through binding with their transcripts." (PMID 36266723, 2022). "To investigate the mechanism behind CI-induced cell cycle arrest and apoptosis, we employed PPI (protein–protein interaction) to identify the top 10 genes related to tumor, cell cycle, and apoptosis, including CDK1 and Bcl2." (PMID 35450041, 2022). "Downregulating CDK1 in NCI-H295R cells also suppressed the growth of these tumor cells in nude mice." (PMID 36184616, 2022). "Alsterpaullone, Flavopiridol, and RO-3306 are CDK1 inhibitors and have been shown to increase drug efficacy and decrease tumor growth." (PMID 35681641, 2022). "The correlation between TOP2A and CDK1 remained significant in both the tumour subtypes (r:0.58, p:0.004; r:0.79, p:0.02 in proliferative, and normal-like subtypes, respectively)." (PMID 36345011, 2022). "Studies have shown that the abnormal activation of CDK1 in CDKs in various tumors leads to the development of tumor cells by regulating the cell cycle G2/M." (PMID 36098680, 2022). "CDK1 expression can be modified by ZWINT to promote HCC progression with increased tumor size and number." (PMID 35681641, 2022). "Based on the TCGA database, the data from the present study indicated that CDK1 expression was positively related to MDSC infiltration in almost all tumor types (except for DLBC, HNSC-HPV+, and UCS)." (PMID 35681641, 2022). "We observed a direct dose- and time-dependent relationship between RP-6306 plasma concentration and inhibition of CDK1 Thr14 phosphorylation in tumours, with an EC50 of 2.8 nM (95% confidence interval 2.0–3.4 nM), indicating potent on-target activity in vivo." (PMID 35444283, 2022). "CDK1 not only broadens the approach to tumor therapy based on control of the cell cycle but also plays an important role in cell cycle development." (PMID 36004205, 2022). "In vitro experiments confirmed the high expression status of CDK1 in tumor tissues, adding credibility to its use as a potential therapeutic target for differentially highly expressed tumors." (PMID 36090896, 2022). "Previous studies have also reported strong associations of EIF4A3 with different cell cycle regulatory genes (CDK1 and CDK2), tumor-associated transcription factors, chemokine signaling pathways and spliceosome signaling pathways." (PMID 35139874, 2022). "Combination treatment with the specific CDK1 inhibitor RO-3306 and apigenin significantly suppressed tumor growth in an orthotopic BC xenograft animal model." (PMID 35729325, 2022). "Consistent with our in vitro data, NCC_CDS1_X1_C1 and NCC_CDS2_C1 tumor explants from adavosertib-treated mice demonstrated a decrease in CDK1 phosphorylation (Y15) and increased PARP cleavage compared with vehicle control." (PMID 35315355, 2022). "Three genes (SQSTM1, G6PD, and CDK1) were upregulated in the tumor tissues compared to the HCC normal tissues in the TCGA-LIHC dataset." (PMID 35711939, 2022).
tumor (continued). "Three genes (SQSTM1, G6PD, and CDK1) were classified into risky group with HR >1 related to poorer prognosis and presented higher expression levels in tumor tissues than in normal tissues." (PMID 35711939, 2022). "Eight hub genes (CDK1, EGFR, UBC, MYC, CCNB1, RHOB, CDC6, and CDC20) have tumor suppressor functions, while five hub genes (CDK1, EGFR, FYN, UBC, and CCNB1) are protein kinases as well." (PMID 35632527, 2022). "In 2018, tumor cells with radioactive inhibition of CDK1 activity were found to have a weaker clone level, further demonstrating the potential of CDK1 in tumor therapy." (PMID 36004205, 2022). "We compared the differences in CDK1 phosphorylation levels in normal and primary tumor tissues using the CPTAC dataset analysis in the UALCAN database." (PMID 36090896, 2022). "The corresponding clinical and pathological points for each patient, such as gender, age, histological grade, tumor stage, and expression of CDK1, were calculated and added together to obtain the total points." (PMID 35681641, 2022). "Cell trajectories showed that the expression of PRKCD, PRKAA2, CDK5, and CDK1 genes increased from hepatocytes to tumor cells." (PMID 36120466, 2022). "In addition, CDK1 expression was significantly correlated with oncogenic genes, proteins, cellular components, myeloid-derived suppressor cell infiltration, ESTMATEScore, and signaling pathways associated with tumor development and progression and tumor microenvironments." (PMID 35681641, 2022). "CDK1 (cyclin-dependent kinase 1) promotes the transition from the G2 to M phase of the cell cycle, thereby promoting the proliferation of tumor cells." (PMID 35600868, 2022). "Molport-003-703-800 is a new targeted drug that demonstrated a potent affinity with CDK1 and anti-tumor activity in vitro, making it a potential candidate drug for CCA chemotherapy." (PMID 36224755, 2022). "Down-regulation of CDK1 significantly restrained adhesion between tumor cells and matrix and cell invasion in human SW13 cells." (PMID 35123514, 2022). "In TCGA cohort, the tumor stage and radical resection were as adjusted factors in the multivariate Cox regression model and regression coefficients (β) of CDK1 and CDK4 were calculated." (PMID 35193513, 2022). "Compared with the corresponding normal tissue, the qRT-PCR ultimately confirmed the upregulation of SFN, PRKAA2, PITX2, and CDK1 in tumor tissue." (PMID 35592706, 2022). "CDK1 inhibitor RO3306 in combination with sorafenib treatment significantly decreased tumor growth in patient derived xenograft (PDX) tumor models." (PMID 35053461, 2022). "In this study, we investigate how RRM2 mediates the anti-tumor effect of PECT on GBM via reducing CDK1 protein expression and examined the functional significance of autophagy and cell cycle in GBM treatment." (PMID 35651787, 2022). "The protein levels of PRKAA2, SFN, and CDK1 were upregulated in tumor tissue on the basis of the Human Protein Atlas (HPA) database." (PMID 35592706, 2022). "The results showed that CDK1 expression was significantly higher in tumor tissues compared with normal tissues." (PMID 36078096, 2022). "We divided tumor cases into high- and low-expression groups according to CDK1 expression levels and investigated the correlation between CDK1 expression and the prognosis of patients with different tumors using the TCGA dataset." (PMID 36090896, 2022). "Anthracyclines, mitotic inhibitors, anti-tumor antibiotics, and CDK1 inhibitors are key classes for repositioning against coronavirus infection." (PMID 35831333, 2022). "We found that PRKCD, PRKAA2, CDK5, and CDK1 genes were increased in the progression from hepatocytes to tumor cells." (PMID 36120466, 2022). "Shikonin arrests the cycle of tumor cells by regulating the expression of cycle-related proteins, such as cyclin A, cyclin B, CDK1, and CDK2." (PMID 35847368, 2022). "As for CDK1, the expression of CDK1 only had a positive correlation with tumor purity (cor = 0.283, p = 0.015)." (PMID 35693556, 2022).
tumor (continued). "More importantly, anti-CDK1 inhibitor treatment reduced tumor growth in imatinib-resistant and imatinib-sensitive gastrointestinal mesenchymal tumor xenograft mice models, reversing the chemoresistant and sensitive situation." (PMID 36090896, 2022). "For the blocking effect of anlotinib on the tumor cell cycle, it was validated in this study by detecting the levels of CDK1 and cycle B affecting the G2/M phase." (PMID 33438349, 2021). "Further survival analyses, ROC curve analysis and representative image analysis, selected 5 hub genes, including CDK1, CDC20, CCNB1, CENPF, and MAD2L1, that were associated with early diagnosis, tumour stage, and poor outcomes of HCC." (PMID 34603487, 2021). "Conversely, an increase in tumor purity was positively correlated with the expression of CDK-1 in COAD due to CD4+cells and CDK-4 in COAD and READ resulting from a fraction of immune cells." (PMID 33732631, 2021). "In summary, this work report that miR-195-3p overexpression enhances the radiosensitivity of NPC cells and inhibits tumor growth by targeting CDK1." (PMID 34585634, 2021). "As a direct downstream target of miR-485-5p, PKMYT1 was initially identified as a negative regulator of the normal cell cycle transition by inhibiting CDK1-cylin B complex via phosphorylating Tyr14/Tyr15, which is more critical for tumor cell proliferation." (PMID 34856993, 2021). "CDK1 expression is increased in most tumors, including NPC, and CDK1 inhibitors significantly inhibit tumor growth." (PMID 34585634, 2021). "Studies report that high CDK1 expression level is an independent predictor for tumor recurrence in one and five years, and compounds that target CDK1 can be novel antitumor reagents." (PMID 34556750, 2021). "Multiple studies showed the ability of CDK1 inhibitors to induce G2/M phase cell cycle arrest and apoptosis in tumour cells, both in vitro and in vivo." (PMID 34503199, 2021). "DUX4 was shown to inhibit CDK1 activity, likely by preventing CDK1 binding to its targets and supporting a tumor suppressor function of DUX4 in colon cancer." (PMID 34943834, 2021). "IHC showed that circSLC7A11 knockdown attenuated the expression of CDK1, cyclin B1, and N-cadherin, but enhanced that of E-cadherin in xenograft tumor tissues, consistent with the in vitro results." (PMID 34844614, 2021). "Because it is crucial for mitosis, the aberrant expression of the CDK1 gene correlates with various tumours." (PMID 34603487, 2021). "It is noteworthy that the increase in tumor purity was inversely correlated with the expression of CDK-1 in READ." (PMID 33732631, 2021). "According to a report, the up‐regulation of CDK1 can promote the growth and the proliferation of melanoma tumor cells." (PMID 34586751, 2021). "The CDK1/cyclin B1 complex not only mediates mitochondrial activities during cell cycle progression but also plays a critical role in tumor adaptive resistance." (PMID 33744866, 2021). "Some results strongly suggested that CDK1 acts as a tumor-specific mediator, affecting apoptin-induced cytotoxicity in HCC cells." (PMID 33685467, 2021). "We found 15 cell cycle regulatory genes (E2F targets or G2M checkpoint Hallmark genes) upregulated in female Ctnnb1 tumours compared to Ctnnb1 male tumours, including Ccne1 and Cdk1." (PMID 33214683, 2021). "Western blot analysis revealed that expression of cell cycle regulatory factors Cyclin B1 and Cdk1 in tumor tissue decreased significantly in response to treatment with PP*-P8." (PMID 34039418, 2021). "Taken together, these studies imply that CDK1 inhibitors can sensitise tumour cells for radiation therapy, increasing the efficacy of this therapy." (PMID 34503199, 2021). "CDKN3 itself is a phosphatase, which acts as a tumor suppressor and mediates the cell cycle by dephosphorylation of cyclin-dependent kinases which mainly include CDK1." (PMID 34795689, 2021).
tumor (continued). "Collectively, DEPDC1B knockdown induces cell apoptosis, leads G2 phase arrest, and inhibit growth and migration in tumor mediated by CDK1." (PMID 34032605, 2021). "Recent studies have shown that CDK1 not only regulates the cell cycle, but also plays an important role in the proliferation of tumor cells." (PMID 34023852, 2021). "The treatment selectively killed stem cell-derived tumour components, which shows potential for targeting CSCs via CDK1 inhibition." (PMID 34503199, 2021). "CDK1 inhibitors such as flavopiridol have shown synergistic antitumor effects through increasing apoptosis and decreasing proliferation among tumor cells when combined with conventional chemotherapeutics." (PMID 34844614, 2021). "In OS, a majority of differentially expressed genes were described as being involved in cell cycle regulation, including Cdk1 and cyclin B2, which were found upregulated in this tumor." (PMID 34358066, 2021). "As expected, the regulation of G2/M checkpoint by CDK1 gene (Cyclin-Dependent Kinase 1) was identified as an essential factor in multiple tumor progressions." (PMID 34795689, 2021). "For the blocking effect of anlotinib on the tumor cell cycle, it was validated in this study by detecting the levels of CDK1 and cycle B which affect the G2/M phase." (PMID 33438349, 2021). "For instance, overexpression of CCNB1 and CDK1 induces tumor growth and metastasis in human breast cancer." (PMID 33627711, 2021). "We verified the increased RNA expression of MMEJ-related H2ax, Fen1, Cdk1, Plk1, and Polθ and decreased RNA expression of Mdc1 in the MmuPV1 tumor tissues by real-time RT-qPCR." (PMID 34343212, 2021). "Both drugs inhibited tumour growth and reduced tumour weight, but only 5MeOIndox reduced CDK1/cyclin B1 complex levels." (PMID 34503199, 2021). "In human tumor cells, Cdk1 promoted the phosphorylation of ribose-phosphate diphosphokinase 1 (PRPS1) at S103, and the loss of phosphorylation at S103 altered the cell cycle, which was similar to the alteration of the cell cycle observed in ΔBbTdp1 mutants." (PMID 34378960, 2021). "For any therapy, but especially for a therapy targeted against CDKs, it seems essential to screen patients in order to ensure that PDAC tumour cells are indeed overexpressing CDK1." (PMID 34503199, 2021). "•An increase in tumor purity was positively correlated with the expression of CDK-1 in COAD due to CD4+ cells and CDK-4 in COAD and READ resulting from a fraction of immune cells." (PMID 33732631, 2021). "We found that CDK1 was over expressed in endometrioid endometrial cancer and the expression of CDK1 in cytoplasm increased as tumor grade progressed." (PMID 33758599, 2021). "The first proposed anticancer mechanism of CDK1 inhibition is halting cell cycle progression of tumour cells at the DNA structure checkpoint, resulting in G2/M phase cell cycle arrest." (PMID 34503199, 2021). "It is worth noting that overexpression of CDK1 increased tumorigenic potential and the capacity for tumor initiation." (PMID 34895070, 2021). "The arrest of cells in G2/M phase was accompanied by a reduced level of CDK1 and cyclin B1, suggesting that the mechanism of tumour growth inhibition was mediated through reduced CDK1/cyclin B1 activity." (PMID 34503199, 2021). "BITC was found to induce apoptosis to suppress tumor growth in nude mice by downregulating cyclin B1 and Cdk1 expression." (PMID 33263014, 2020). "Cyclin B1/CDK1 complex mediate mitochondrial activities in cell cycle progression and stress response as well as metabolism energy reprogramming in tumor adaptive resistance." (PMID 33339392, 2020). "Phosphorylation of CDK1 was diminished, whereby down-regulation of CDK1 and its binding partner, Cyclin B, inhibited tumor growth." (PMID 32512849, 2020).